PRDX4 (peroxiredoxin 4)
Description:
Thiol-specific peroxidase that catalyzes the reduction of hydrogen peroxide and organic hydroperoxides to water and alcohols, respectively. Plays a role in cell protection against oxidative stress by detoxifying peroxides and as sensor of hydrogen peroxide-mediated signaling events. Regulates the activation of NF-kappa-B in the cytosol by a modulation of I-kappa-B-alpha phosphorylation.
Synonyms: AOE37-2; AOE372; HEL-S-97n; PRX-4
Tractability: Small molecule: a structure with a bound ligand is known; it has a binding pocket of medium quality. Antibody: its Gene Ontology location is reachable by antibodies, with high confidence; UniProt predicts a signal peptide or a membrane-spanning region. PROTAC: ubiquitination databases record sites on it; its protein half-life has been measured.
Target class: Enzyme; Oxidoreductase
Gene: Protein-coding gene on chromosome X (23,664,262 to 23,686,399, forward strand). Ensembl gene ENSG00000123131.
Subcellular location: Cytoplasm; Endoplasmic reticulum
Subcellular location (Human Protein Atlas): Endoplasmic reticulum; Cytosol
Pathways (Reactome):
Immune System: Neutrophil degranulation
Gene Ontology:
Molecular function: molecular adaptor activity; molecular sequestering activity; protein binding; thioredoxin-dependent peroxiredoxin activity; thioredoxin peroxidase activity; antioxidant activity; identical protein binding; oxidoreductase activity; peroxiredoxin activity
Biological process: hydrogen peroxide catabolic process; I-kappaB phosphorylation; response to oxidative stress; cellular oxidant detoxification
Cellular component: cytoplasm; cytosol; endoplasmic reticulum; extracellular exosome; nucleus; extracellular region; ficolin-1-rich granule lumen; secretory granule lumen
Homologues: Orthologues: chimpanzee PRDX4 (100% identical), dog PRDX4 (93% identical), guinea pig PRDX4 (90% identical), mouse Prdx4 (90% identical), rat Prdx4 (89% identical), pig PRDX4 (88% identical), rabbit PRDX4 (86% identical), macaque PRDX4 (85% identical), tropical clawed frog prdx4 (77% identical), zebrafish prdx4 (76% identical), Drosophila melanogaster Prx4 (59% identical), Caenorhabditis elegans prdx-3 (46% identical). Paralogues in human: PRDX3 (52% identical), PRDX1 (51% identical), PRDX2 (51% identical), PRDX6 (23% identical).
Diseases named in the same sentence as PRDX4 in open-access papers:
PRDX4 is named in the same sentence as 130 diseases in open-access papers, as found by Europe PMC text mining. Sharing a sentence is not in itself a finding about the gene and the disease. The quoted sentences say what the papers report.
breast carcinoma (21 papers, 2007 to 2025). "Prior work has shown the overexpression of PRDX4 to be associated with poor overall survival rates, shorter relapse-free survival among breast cancer patients, and metastasis." (PMID 39057065, 2024). "Another salient example of a cancer-specific enhancer linked to a male breast cancer upregulated gene is PRDX4." (PMID 37685859, 2023). "Overall, SFN, YWHAB, TXNDC12, MYL6B, and PRDX4 expressions are significantly associated with breast cancer patient survival." (PMID 37128318, 2023). "PRDX4 has also been shown to be associated with more advanced breast cancer tumors, which could also contribute to treatment resistance." (PMID 39057065, 2024). "Meanwhile, IGLC2 and PRDX4 were downregulated 73-fold and sevenfold, respectively, and their high expression is associated with better disease-specific or relapse-free survival in breast cancer." (PMID 37391754, 2023). "TXNDC12, FN1, and PRDX4 have conflicting expressions in breast cancer patient blood compared to control samples in relation to secretory protein expression." (PMID 37128318, 2023). "For bone metastasis, sEV release of L-plastin and peroxiredoxin-4 (PRDX4) from MDA-MB-231 cells mediated breast cancer-induced osteolysis." (PMID 36212432, 2022). "Our correlative results suggest that breast cancer patients with high levels of PRDX4 may be targeted using compounds such as Con A, pending confirmation that increased protein levels are also prognostic in breast cancer patients." (PMID 41373732, 2025). "Notably, L-plastin cooperates with secreted peroxiredoxin-4 (PRDX4) to exacerbate breast cancer-induced osteolysis, collectively facilitating skeletal metastasis progression." (PMID 40564894, 2025). "Thus, the role of PRDX4 as a potential mechanistic marker and potential target in treatment-resistant breast cancer deserves future exploration." (PMID 39057065, 2024). "High expression of PRDX4 has been reported in a variety of cancers including breast cancer; on the other hand, increased tissue level of PRDX4 was found to be correlated with a better survival rate in breast cancer patients." (PMID 37719007, 2023). "We selected PRDX4 for this example because this gene is involved in breast cancer metastasis." (PMID 37685859, 2023). "Similarly, PRDX4 is overexpressed in several cancers such as gastric cancer, lung cancer, and breast cancer." (PMID 37685859, 2023). "Through the regulation of redox balance, oxidative protein folding, and regulation of hydrogen peroxide signaling, PRDX4, a 2-Cys antioxidant of peroxiredoxins, participates in the progression of breast cancer, prostate cancer, ovarian cancer, colorectal cancer, and lung cancer." (PMID 35804959, 2022). "The same study demonstrated that peroxiredoxin-4 (PRDX-4) is also implicated in this process, and that higher levels of both L-plastin and PRDX-4 are associated with a higher risk to develop bone metastasis in breast cancer patients." (PMID 36612237, 2022). "Similar to MDA‐MB‐231 breast cancer cells, K562 cells produced and released L‐plastin and PRDX4." (PMID 33587325, 2021). "Additionally, in other types of epithelial cancers such as oral cavity squamous cell carcinoma, breast cancer, ovarian cancer, and lung cancer, overexpression of PRDX4 correlates with the metastatic potential again implicating an alternative possible role for PXDN in regulating metastasis." (PMID 31234468, 2019). "High PRDX4 expression led to significantly decreased survival in non-stratified samples (p = 0.018), and also in late stages (p = 0.00049), this marker is associated with oxidative stress, conforming its associated with breast cancer progression and metastasis." (PMID 37128318, 2023). "We highlight two examples of previously unannotated cancer-cell-specific enhancers of ANXA2 and PRDX4 gene expression and show evidence for super-enhancer regulation of LAMB3 and CD47 in male breast cancer cells." (PMID 37685859, 2023).
breast carcinoma (continued). "In support of our concept to target PRDX4 as future GBM therapy, a small molecule (piperlongumine) which increases ROS levels in breast cancer cells induced cancer cell death in vitro and inhibited tumor growth in vivo." (PMID 22916164, 2012). "PRDX4 is the only member of the PRDXs family located in the endoplasmic reticulum, and its expression is upregulated in multiple tumors, including OSCC, lung cancer, prostate cancer, colorectal cancer, ovarian cancer and breast cancer." (PMID 35350568, 2022). "However, ERO1 loss of function is not fully compensated by PRDX4 and other oxidases: indeed, in previous work, we demonstrated a selective impairment of VEGFA-mediated angiogenesis in ERO1-devoid breast cancer under hypoxic conditions." (PMID 36063727, 2022). "Karihtala and colleagues observed that staining for PRDX2 and PRDX6 was negative in half of breast cancer cases, whereas PRDX1, PRDX3, PRDX4 and PRDX5 showed stronger expression levels." (PMID 17980029, 2007).
lung carcinoma (18 papers, 2011 to 2025). "PRDX4, as an antioxidant, play a role protecting cells from the oxidative stress damage caused by ROS in acute promyelocytic leukemia and lung cancer." (PMID 24098506, 2013). "PRDX4 was found to promote human lung cancer progression via the modulation of specific phosphokinase signaling." (PMID 35512017, 2022). "In conclusion, PRDX4 overexpression modulated tumor microenvironment and promoted tumor development in the mouse urethane-induced lung cancer model." (PMID 33456675, 2020). "Peroxiredoxin 4 (PRDX4), initially reported as an antioxidant, is overexpressed in lung cancer and participates in its progression." (PMID 33456675, 2020). "The relationship between PRDX4 overexpression and AP-1 activation has been well elucidated in the A549 lung cancer cell line." (PMID 33456675, 2020). "In comparison to massive studies on lung cancer progression, PRDX4's role in lung cancer development is still undetermined." (PMID 33456675, 2020). "In vitro, knockdown of PRDX4 in the A549 lung cancer cell line results in the formation of fewer colonies and reduced Matrigel invasion, whereas overexpression of PRDX4 enhances anchorage-independent colony formation and Matrigel invasion." (PMID 33456675, 2020). "As a protein closely related to cancer, PRDX4 has been found to be overexpressed in lung cancer, especially adenocarcinoma." (PMID 33456675, 2020). "SRX also interacts with PRDX4 preferentially and knockdown of PRDX4 results in similar effects, suggesting a tumor driver role in lung cancers." (PMID 22916164, 2012). "This is in line with a previous study using lung cancer models, suggesting that PRDX4 overexpression contributes to multiple cancer types." (PMID 22916164, 2012). "In the present study, we found that PRDX4 expression was increased highly in most human GBMs, as in prostate cancers, lung cancers, and osteosarcomas." (PMID 22916164, 2012). "Furthermore, the tumorigenic role of PRDX4 has been confirmed in lung cancer, leukemia, and glioblastoma." (PMID 40281661, 2025). "Moreover, the tumor-promoting role of PRDX4 has been demonstrated in lung cancer, leukemia, and glioblastoma." (PMID 36969053, 2023). "Since it is well known that EGFR mutations usually lead to the abnormal expression of itself and promotes cellular proliferation in lung cancer, we investigated the roles of PRDX4 in the proliferation of two human LUAD cell lines, A549 cells (EGFR wild-type) and PC-9 cells (EGFR mutant)." (PMID 31588184, 2019). "PRDX4 levels are increased in glioblastoma cell, prostate cancer and lung cancer." (PMID 26061816, 2015). "Knockdown of PRDX1 or PRDX4 significantly reduced the activation of c-Jun and thus repressed AP-1 mediated promoter activity, which may contribute to the changes of lung cancer cell phenotype." (PMID 26061816, 2015). "PRDX4 was critical for the activation of AP-1 signaling, and depletion of PRDX4 leads to reduced phosphorylation of c-Jun and decreased expression of MMP9, which contributes to the malignancy of human lung cancer cells." (PMID 33456675, 2020). "Although no key players in lung cancer development were found to be significantly changed after PRDX4 overexpression in the whole-transcript array, other analyses (RT-PCR and WB) revealed some important positive findings." (PMID 33456675, 2020).
diabetes (17 papers, 2011 to 2025). "To understand the molecular pathology of PRDX4 deficiency–induced retinal injury in diabetes, we determined the levels of ER stress–associated markers in mouse retinas." (PMID 39706273, 2024). "The aim of this study was to investigate peroxiredoxin 4 (Prx4), a proposed novel biomarker of oxidative stress, and its association with and capability as a biomarker in predicting (cardiovascular) mortality in type 2 diabetes mellitus." (PMID 24586984, 2014). "Thus, loss of the protective mechanisms afforded by PRDX4 to maintain ER redox balance may be a critical determinant in the development of β-cell dysfunction in diabetes." (PMID 40136648, 2025). "Streptozotocin-induced mouse model of diabetes and high glucose (HG)–induced Müller cells were utilized to assess the impact of PRDX4." (PMID 39706273, 2024). "Our findings demonstrated that GFAP expression in Müller cells increases as diabetes progresses and provided the first evidence that PRDX4 suppressed reactive gliosis of Müller cells during DR." (PMID 39706273, 2024). "PRDX4 overexpression in mice relieves streptozotocin (STZ)-induced diabetes by repressing oxidative stress and inflammatory responses." (PMID 39706273, 2024). "Numerous studies have demonstrated the potential of PRDX4 as a biomarker for many diseases, such as diabetes and stroke." (PMID 36969053, 2023). "Considering the protective role of PRDX4 in diabetes and its complications, we reasoned that PRDX4 may be involved in DR development and set out to investigate the exact role of PRDX4 in DR." (PMID 39706273, 2024). "PRDX4 has been reported in the serum of patients with diabetes and IPF." (PMID 33895140, 2021). "In particular, Prdx4 may protect from diabetes and its chronic complications, by reducing oxidative stress levels." (PMID 32316601, 2020). "In addition, we previously reported regarding the antioxidant effects of PRDX4 in Tg mice in the models of diabetes mellitus, atherosclerosis, and nonalcoholic fatty liver disease." (PMID 31888585, 2019). "In β-cells, PRDX4 overexpression was shown to increase proinsulin biosynthesis and insulin secretion and protect mice from STZ-induced diabetes." (PMID 40136648, 2025). "AAE also promotes cell regeneration and restores islet cell function via Peroxiredoxin 4 (PRDX4) overexpression, which alleviates diabetes mellitus." (PMID 36673411, 2023). "∗The Prdx4 gene was not modulated by progesterone according to defined criteria, but it was included since it has been studied in the diabetes context and β-cell physiology." (PMID 33014046, 2020). "Whether PRDX4 hyperoxidation in diabetes models is due to excess ERO1β activity is not known, but ERO1β overexpression promotes ER hyperoxidation, which consequently leads to inactivation of PRDX4." (PMID 40136648, 2025). "Interestingly, Prdx4 plasma levels were shown to be significantly higher in individuals with type 2 diabetes mellitus than in nondiabetic patients, which could represent a mechanism to compensate oxidative stress in this condition." (PMID 33014046, 2020). "Whereas Prdx4-knockout (Prdx4−/y) mice show no apparent phenotypic abnormality except for testicular atrophy, it has been reported that the human Prdx4 transgene renders nongenetic models of NAFLD and/or type 2 diabetes mellitus resistant to the progression of the pathology." (PMID 30050648, 2018).
prostate carcinoma (15 papers, 2011 to 2025). A carcinoma that arises from epithelial cells of the prostate gland. "An overexpression of PRDX4 has been observed in many cancers including prostate cancer and has been linked with heightened tolerance of cancers to oxidative stress." (PMID 37627612, 2023). "Other antioxidant proteins, such as peroxiredoxin 4, were also shown to be highly expressed in prostate cancer patient specimens and cultured prostate cancer cell lines and promoted prostate cancer growth and survival." (PMID 41008967, 2025). "For example, peroxiredoxin 4 (Prdx4), which belongs to one of the peroxiredoxin family members, was found to be secreted by breast and prostate cancer cells and capable of promoting osteoclastogenesis." (PMID 39263840, 2024). "We have previously established that osteoclastogenesis can be induced by both antioxidant enzyme peroxiredoxin‐4 (PRDX4) and L‐plastin, which is an actin‐bundling protein secreted by human breast and prostate cancer cells." (PMID 33587325, 2021). "Therefore, further exploration of the upstream regulatory links of PRDX4 affecting the progression of prostate cancer seems to be what we should do in the future." (PMID 41445793, 2025). "We continue to analyze the proteins that may interact with PRDX4, laying the foundation for exploring the molecular mechanisms of PRDX4 in prostate cancer in the future." (PMID 41445793, 2025). "Exploring the impact of PRDX4 on other phenotypes of prostate cancer cells could be one of our research directions in the future." (PMID 41445793, 2025). "We silenced PRDX4 in prostate cancer (22RV-1) cells using siRNA." (PMID 41445793, 2025). "Interestingly, PRDX4 was also identified as a potential therapeutic target for prostate cancer, suggesting a possible shared mechanism for androgens in both prostate and breast tissues." (PMID 39057065, 2024). "Protein network analysis and clustering of differentially expressed proteins revealed new targets such as DDAH1, ARG2, EIF4A3, Par4, PPA2, Prdx3 and Prdx4, which need further validation to define their potential application in clinical relevance in prostate cancer." (PMID 21347291, 2011). "Among the upregulated proteins, the peroxiredoxin 4 (PRDX 4) protein was significantly upregulated and has been demonstrated to play a critical role in prostate cancer cell growth and radioresistance." (PMID 37627612, 2023). "In conclusion, the current study identified potential novel biomarkers for prostate cancer development and/or progression such as eIF4A3, DDAH1, ARG2, Prdx3, and Prdx4 from proteomic data using systems biology approach." (PMID 21347291, 2011). "In the future, if PRDX4 is combined with PSA, PAP, and PCA3 for the diagnosis of prostate cancer, it may greatly improve the current limitation of poor PSA specificity and further enhance the sensitivity of diagnosing PCa." (PMID 41445793, 2025).
hepatocellular carcinoma (13 papers, 2015 to 2025). A malignant tumor that arises from hepatocytes. "Further investigation revealed that the β-catenin downstream gene ID2 is responsible for the oncogenic activity of PRDX4 in hepatocellular carcinoma (HCC) cells, promoting anchorage-independent growth and anoikis resistance." (PMID 41445793, 2025). "LncRNA TP53TG1 inhibits hepatocellular carcinoma growth and metastasis by affecting the PRDX4/β-catenin axis." (PMID 34408984, 2021). "lncRNA TP53TG1 suppressed the progression of hepatocellular carcinoma through interacting with PRDX4 to promote its ubiquitin-mediated degradation, leading to inactivation of the WNT/β-catenin pathway." (PMID 34244473, 2021). "However, decreased PRDX4 repressed cell proliferation and triggered cell death pathways in hepatocellular carcinoma cell lines, suggesting the potential role of PRDX4 as activators or inhibitors in hepatocellular carcinoma with different stages and phenotypes." (PMID 32382548, 2020). "Antioxidants like PRDX4 may suppress liver inflammation and prevent hepatocellular carcinoma but may exacerbate pulmonary inflammation and promote the development of lung adenocarcinoma." (PMID 33456675, 2020). "This was independently confirmed by both siRNA silencing and warfarin knock-down of VKOR enzymatic activity in human hepatoma HepG2 cells after Ero1 α/β isoforms and peroxiredoxin IV (PRDX4) were first functionally silenced, demonstrating that VKORC1 alone can facilitate OPF." (PMID 26264021, 2015). "In our previous study in hepatocellular carcinoma (HCC), we found that PRDX4 inhibits the initiation of HCC but plays a complex role in tumor progression." (PMID 33456675, 2020). "PRDX4 is overexpressed in a variety of tumor tissues, and inhibits anoikis resistance through the β-catenin/ID2 pathway, thereby promoting the growth and metastasis of hepatocellular carcinoma cells." (PMID 36092898, 2022).